CD86 (CD86 molecule)
Diseases named in the same sentence as CD86 in open-access papers (continued):
Sharing a sentence is not in itself a finding about the gene and the disease.
melanoma (continued). "Collectively, these findings illustrate that recombinant mRNA vaccine triggers a Schwann cell‐like differentiation in melanoma cells via the EGR3 gene and bolster immune infiltration through the CD86 gene, ultimately resulting in effective tumor control." (PMID 38973154, 2024). "For verification, tissue sections were examined by fluorescence staining, showing co-expression of CD74 and CD86 in eight cancer types (BRCA, BLCA, esophageal squamous cell carcinoma, COAD, STAD, melanoma, cervical cancer, and osteosarcoma)." (PMID 38582956, 2024). "SpatialDB was used to determine the overlap between the distributions of CD74, the macrophage marker CD68, and the M1 macrophage marker CD86 in PRAD and melanoma tissues." (PMID 38582956, 2024). "In the here used human M-MDSC model, we observed that upon exposure to melanoma CM, moMDSCs further acquired a suppressive phenotype, characterized by the upregulation of CD14, CCR5, MerTK, and the downregulation of HLA-DR and CD86." (PMID 38343540, 2024). "Co-incubation of dying melanoma cells with human monocyte-derived DCs indicated that only MTX and Hyp-PDT increased surface expression of the DC-maturation markers CD86 and HLA-DR." (PMID 34453119, 2022). "We have also analyzed the expression of costimulatory receptors CD86 and ICOSLG on TAM from B16-F10 melanoma and CT26 colon carcinoma models." (PMID 35503656, 2022). "There are studies characterizing the tumor-conditioned DCs; melanoma cells induce the enhanced expression of CD80, CD86, MHC class I, and MHC class II molecules on immature DC." (PMID 36194602, 2022). "We compared their characteristics to the melanoma TAMs, evaluating the expression of CD11b, F4/80, Ly6C, CSF1R, iNOS, CD40, CD86, MHCII, Arg1, CD163 and CD206 expression by flow cytometry." (PMID 34572807, 2021). "While PTT alone (ICG-PLGA-PTT) increased CD80, CD86, and MHC-I expression, the addition of NextA further increased these expression levels on melanoma cells in vitro." (PMID 31963449, 2020). "UV irradiation also induced ICD of B16/F10 melanoma cells, as indicated by HMGB1 release and upregulation of MHC-II and CD86, which remained higher even upon poly I:C addition, on cDC1s exposed to B16/F10 TCL." (PMID 30961656, 2019). "Melanoma-patient-derived sera induced higher levels of CD163+CD206+ macrophages compared to healthy-donor-derived sera, while HLA-DR and CD86 expression remained unchanged." (PMID 30712866, 2019). "Through co-expression of PD-1, CTLA-4, and PD-L1, melanoma cells are able to inhibit antigen presenting cells such as DCs by direct binding of CD80 and CD86 through CTLA-4 and by engagement of PD-L1 through PD-1." (PMID 31192129, 2019). "Incubation of primary human monocytes (HuMo) with sEVs derived from A375 melanoma cells decreased the expression of co-receptor protein CD40 and HLA-DR, while the mean fluorescence intensity of HLA-ABC molecules and CD86 remained largely unchanged." (PMID 31269655, 2019). "The slices of 4T1 and melanoma models exhibited an increased number of CD4, CD8, and CD86 in the Tα1-Fc group compared with that in the Tα1 group." (PMID 30120362, 2018). "In summary, Tα1-Fc inhibited the tumor growth on melanoma with an increased expression of IFN-γ, IL-2, and CD86 and of tumor-infiltrating CD4+ T and CD8+ T cells." (PMID 30120362, 2018). "Mature DCs induce co-stimulation through CD40, CD80, CD86 and OX40L while they circulate in peripheral sites regulating innate and adaptive anti-melanoma immunity." (PMID 29285320, 2017). "Consistent with a previous study on melanoma patients, we detected variable level of CD80, CD83 and/or CD86 expression on CD14+HLA-DR−/low MDSC in the PB and/or ascites from OC; however, their functional significance remains elusive." (PMID 29100353, 2017). "Examples include PD-L1, HLA-G and CD86, shown to induce immunosuppression in NK and CD8+ cells following their cross-dressing with membranes taken from melanoma or multiple myeloma." (PMID 25671577, 2015).
melanoma (continued). "Altogether, these results suggest that HIFU increases the expressions of CD86 and ICAM-1 in melanoma tumor likely through miRNA." (PMID 26485753, 2015). "Immature DCs efficiently phagocytosed melanoma Apo-Nec cells and matured after phagocytosis as evidenced by increased expression of CD83, CD80, CD86, HLA class I and II, and 75.2 ± 16% reduction in Dextran-FITC endocytosis." (PMID 18221542, 2008). "Additionally, B7-H2 (CD86) mRNA was found in macrophages, PDCD1 (PD-1) mRNA was present in T cells (as expected), and TNFRSF14 and TNFSF9 mRNAs were observed in both T and melanoma cells." (PMID 40647495, 2025). "In support of these reports, publications indicate that CD80 and CD86 expression in melanoma patients does not effect the prognosis." (PMID 37614091, 2024). "In our current analyses, we found that pyroptosis is significantly associated with the increased expression of multiple immune checkpoint factors in the melanoma microenvironment, such as PD-1/PD-L1, CTLA4, TIM3, LAG3, and immune activation-related molecules, including OX-40, CD40, and CD86." (PMID 36513682, 2022). "Detailed analysis of tumor-infiltrating myeloid cells from melanoma patients revealed that the CD206+ Macro_C1QC subset also expressed high levels of HLA-A (MHC I) and CD86, as well as ICOSLG, and low levels of CD274, as we had observed in our cross-presenting CD206+ M2a macrophages." (PMID 35503656, 2022). "Melanoma CSCs displayed lower levels of MHC-I (but not MHC-II) and melanoma-associated antigens (e.g., MART-1, ML-IAP, NY-ESO-1, MAGE-A), while displayed higher levels of co-stimulatory molecules CD86 and PD-L1, responsible to their immune-evasive capacity." (PMID 33806296, 2021). "Features including helper T cell polarization toward Th2, decreased expression of dendritic cell (DC) costimulatory marker CD86, and decreased CD8+ T cells differentiated melanoma SLNs from control lymph nodes obtained from patients undergoing prophylactic mastectomy." (PMID 28424693, 2017). "DCs matured in vitro in the presence of melanoma EVs demonstrated significantly impaired expression of CD83 and CD86 as well as decreased expression of Th1 polarizing chemokines Flt3L and IL15 and migration chemokines MIP-1α and MIP-1β compared to liposome-treated DCs." (PMID 28424693, 2017). "For example, one study in C57BL/6 mice bearing B16gp melanoma tumors demonstrated that local irradiation with a single high dose of 10 Gy resulted in upregulation of CD70 and CD86 on local DCs, both of which are co-stimulatory molecules involved in T-cell priming." (PMID 28123900, 2016). "Furthermore, we detected the expressions of CD86 and CD80 on the tumor-infiltrating NK cells in vivo 10 days after injection of B16 melanoma cells." (PMID 24349559, 2013). "A recent paper described decreased number of CD11c+ dendritic cells but elevated amount of CD86+ mature DCs in positive compared to negative sentinel lymph nodes in melanoma." (PMID 23418928, 2013). "So, our results show that GGTI-298 treatment does not induce but increases CD86 expression on melanoma cell membranes." (PMID 20140259, 2010). "Furthermore, using a human melanoma model (LB1319-MEL), we demonstrated that in vitro treatment with hIFN-γ and GGTI-298 led to the up regulation of MHC-I and a costimulatory molecule CD86 and down regulation of an inhibitory molecule PD-1L." (PMID 20140259, 2010). "However, the possibility that melanoma cells express the CTLA-4 ligand, CD86, cannot be excluded." (PMID 39837817, 2025). "Without melanoma cells, only a slight upregulation of the expression of CD86 and IL-12 by RD was observed in h-CLAT, suggesting that RD might be a skin sensitizer that induces contact hypersensitivity." (PMID 36671815, 2023). "Given the lack of CD40 costimulatory molecule expression by melanomas, the ligation of CD86 or CD80 with T cell CD28 molecules may be even more critical." (PMID 35162988, 2022).
melanoma (continued). "Although CD86 has been reported to be associated with poor prognosis in chronic lymphocytic leukemia, myeloma, and overall glioma, there was no report of its prognostic value in LGG and melanoma." (PMID 33954112, 2021). "Therefore, PD1 and CD28 expression by T-Exo may be a valuable tool in predicting the best responders to immunotherapy among patients with melanoma, while CD80 and CD86 levels may serve as prognostic biomarkers." (PMID 29755693, 2018). "In contrast to macrophages, the expression of MHCII and CD86 on the surface of DCs could not generally be increased by SNs of melanoma cells whose cell death was modulated by zVAD-fmk." (PMID 25973681, 2015). "The data showed that injection of B16 melanoma cells could significantly increase the expression of CD86, but not CD80, on infiltrating NK cells (from 2.5% to 18.6%)." (PMID 24349559, 2013). "Furthermore, CD80, CD83, and CD86 expression on DC was decreased upon co-culture with melanoma cells and could be partially restored with BRAF inhibition in BRAFV600E mutant melanoma cell lines." (PMID 24194739, 2013). "This suggests that GGTI-298 may increase the membrane localization rather than expression levels of CD86, as we recently demonstrated with FasL protein on the murine melanoma cell line B16F10." (PMID 20140259, 2010). "They revealed that both melanoma-negative and positive SLN LCs expressed lower levels of CD83, CD80, CD86, and HLA-DR (maturation markers) compared to epidermal explant–migrated (mature) LCs." (PMID 38791968, 2024). "Moreover, CY12-RP2 could inhibit melanoma lung metastasis, and abrogated the immunosuppressive effects of PDPN by increasing the proportion of CD3 + CD4 + T cells, CD3 + CD8 + T cells, CD49b + Granzyme B + NK cells, and CD11b + CD86 + M1-like macrophages and the levels of IL-1β, TNF-α, and IFN-γ." (PMID 38167452, 2024). "To ensure that the observed reduction in CD69 and CD86 expression was not due to effects of CK-666 on the APCs, we used Arp3 siRNA to deplete the Arp2/3 complex in B16F1 murine melanoma cells expressing the single chain anti-Igκ Ag." (PMID 31157616, 2019). "By contrast, blockade of MAPK inhibits the negative effect of melanoma cells on the CD80, CD83 and CD86 expression thus restoring the DC co-stimulation." (PMID 29285320, 2017). "SNs of neither mock-treated melanoma cells nor of treated ones altered the expression of the activation markers MHCII and CD86 on macrophages." (PMID 25973681, 2015). "CXCL9, CXCL10, PD-L1, CD86, IL-10, TREM2, GPNMB, IL-4l1 and FOLR2 markers showed widespread expression by most melanoma TAMs, with no definition of a particular macrophage subset, and regardless of whether the tumor was metastasizing or not." (PMID 40406129, 2025). "YTHDF1 might negatively regulate STAT1 and further facilitated melanoma development, but the roles of STAT1 and CD86 in the general network were not large enough to mitigate the trend of disease development." (PMID 32549786, 2020). "However, the modulation of melanoma cell death by zVAD-fmk resulted in tumor cell SNs that induced a significant increased expression of MHCII and CD86 on the surface of macrophages, independent of the death stimulus." (PMID 25973681, 2015). "DC co-cultured with melanoma cells alone did not present significant phenotypic characteristics of DC maturation (CD80: ~5%, CD83: ~6%, CD86: ~10%), and co-culture with UV-irradiated apoptotic cells led to a non-significant increase of CD83 markers only (~11%)." (PMID 22029859, 2011). "DC markers HLA-DR, CD86, CD1c, ILT3 and CD40 did not significantly differ among the outcome groups in mitochondrial populations, however their expression was significantly elevated in the melanoma bad and good outcome groups as compared to HD in the glycolytic cell states." (PMID 37938561, 2023).
melanoma (continued). "However, aPD-1 treatment reduced the number of intratumoral F4/80+CD86+ M1 macrophages, but HLS@SVMAV did not exert a significant influence on M1 macrophages, which is consistent with the observations in the melanoma model." (PMID 34452929, 2021).
Sepsis (68 papers, 2008 to 2026). Sepsis is defined as life-threatening organ dysfunction caused by a dysregulated host response to infection. "Conversely, higher levels of IgD − CD24 − B cell % lymphocytes and CD86 on myeloid DC are associated with an increased risk of sepsis." (PMID 40797460, 2025). "The results suggest that CD86% and HLA-DR% in the first 24 h after admission for acute infection were associated with the occurrence of sepsis and death from sepsis." (PMID 38603712, 2024). "Macrolides increased CD80 but not HLA-DR in patients with chronic sinusitis, while clarithromycin increased HLA-DR in patients with pneumonia and sepsis and increased CD86 in patients with ventilator-associated pneumonia and sepsis." (PMID 39596729, 2024). "A study by the author’s group showed that CD86 gene polymorphisms are related to the expression of CD86 in peripheral blood monocytes and can increase the susceptibility of the human body to sepsis caused by pneumonia." (PMID 38603712, 2024). "CD86 gene polymorphisms play different roles in the pathogenesis of sepsis, some of which interfere with or increase the expression of CD86 genes in monocytes." (PMID 38603712, 2024). "The subsequently experiments suggested that sepsis caused upregulated expression of F4/80, iNOS and CD86, as well as downregulated expression of Arg‐1 and CD206 in renal tissues of mice were reversed by Deh treatment." (PMID 38629726, 2024). "There are reports that acute inflammation during sepsis is associated with suppression of constitutive expression of CD86." (PMID 37367693, 2023). "Similar to mice, humans with sepsis exhibit a loss of CD86 and upregulation of CD80 on circulating monocytes." (PMID 19672303, 2009). "The gene polymorphisms of CD86 may be related to the risk of sepsis with contradictory results in different studies." (PMID 35711689, 2022). "HLA–DR in monocytes has been identified as a crucial immune indicator for sepsis, while CD86 has also been examined in sepsis research." (PMID 40065471, 2025). "In this research, the administration of laminarin resulted in a significant decrease in the expression of CD86, a marker associated with M1 macrophages, in the lungs of septic mice, LPS‐induced RAW264.7 cells, and PBMCs from patients with sepsis." (PMID 40045157, 2025). "The components of antigen presentation (HLA-DR, HLA-DP, CD74, and CLIP) and the co-stimulatory pathway (CD86) were downregulated in patients with sepsis in the ICU compared to healthy volunteers." (PMID 41573541, 2025). "In the CyTOF analyses, monocytes exhibited notably lower CD39, CD86 and HLA–DR expressions in sepsis patients than in mild infection patients." (PMID 40065471, 2025). "The results demonstrated that, in comparison to the control group, the administration of laminarin led to a reduction in the CD86 levels in sepsis patients." (PMID 40045157, 2025). "This prospective observational study explored the predictive value of CD86 in the early diagnosis of sepsis in the emergency department." (PMID 38603712, 2024). "Considering that the mechanism of CD86 in sepsis is still unclear, further multicenter trials and clinical data are required to verify the results." (PMID 38603712, 2024). "This study showed that CD86%, PLT, IL-10, and PCT were independent risk factors for sepsis in patients with infection, while HLA%, PLT, and respiratory rate were independent risk factors for death in patients with sepsis." (PMID 38603712, 2024). "In the sepsis group, the CD86% and NLR were significantly higher, and the HLA-DR% and LMR were significantly lower in the patients who died than in those who survived." (PMID 38603712, 2024). "The model for sepsis (CD86%, platelets, interleukin-10, and procalcitonin) and the model for death (HLA%, respiratory rate, and platelets) had an area under the curve (AUC) of 0.870 and 0.843, respectively." (PMID 38603712, 2024).
Sepsis (continued). "In this study, CD86 was an independent predictor of the occurrence of sepsis, with an AUC of 0.720 and a corresponding cutoff value of 0.92." (PMID 38603712, 2024). "The AUC of CD86% for the prediction of the occurrence of sepsis was 0.720 (0.754 sensitivity and 0.625 specificity), and the cutoff value was 0.92." (PMID 38603712, 2024). "CD80 and CD86 molecules played a differential role in a mouse sepsis model after caecal ligation and puncture (CLP)." (PMID 38355547, 2024). "Complementing our in vitro mechanistic studies, we further examined the role of TRAM in suppressing CD86 expression in vivo, by employing the cecal slurry-mediated sepsis model." (PMID 38162637, 2023). "Studies have demonstrated that DC-related sepsis survival is associated with the expression of co-stimulatory molecules CD80 and CD86." (PMID 37434129, 2023). "TRAM deficient mice are protected from cecal slurry-induced experimental sepsis and retain immune-competent monocytes with CD86 expression." (PMID 38162637, 2023). "In contrast, no significant changes were found in the expression of CD39, CD40, and CD86 on γδ T cells in individuals with sepsis versus healthy individuals." (PMID 35020851, 2022). "A reduction of CD86 and MHCII coupled with an elevation of PD-L1 were shown as key signatures of monocyte exhaustion closely associated with the pathogenesis of sepsis." (PMID 34777396, 2021). "Collectively, the elevation of immuno-suppressors such as PD-L1, SLPI and IL-1R2 and reduction of co-stimulatory molecules such as CD86 contribute to the immuno-suppressive phenotype characteristics of exhausted monocytes observed in clinical sepsis patients." (PMID 34777396, 2021). "This demonstrated the emergence of impaired CD80+CD86+ cells and the reduced T cell ability to stimulate after the induction of sepsis in aged animals." (PMID 33673691, 2021). "To this end, we examined the surface expression HLA-DR and CD86 on DCs derived from the PB of sepsis patients." (PMID 34566996, 2021). "CD1c+ DCs from sepsis patients expressed lower levels of CD86 and HLA-DR during early stage of the disease and remained at significantly lower levels at the later stage compared to their counterparts in the healthy donors." (PMID 34566996, 2021). "Both SP DCs and MLN DCs increased the activation markers, such as MHC class II, CD80, or CD86 during sepsis." (PMID 31323786, 2019). "Mature DCs activate T cells through costimulatory molecules CD80 and CD86 and then are reprogrammed during sepsis to a tolerogenic state." (PMID 30069485, 2018). "In murine studies of sepsis, an important role for CD80 and CD86 antigens in the response to sepsis has been established." (PMID 25302303, 2014). "Upregulation of coinhibitory molecules, PD-L1 and PD-1, and downregulation of positive costimulatory molecules, CD28, CD80, and CD86, are the features of sepsis-induced immunosuppression, reversal of which will improve the survival of septic mice." (PMID 24891762, 2014). "In murine models of graft arterial disease and sepsis, CD80 is associated with proinflammatory cytokine stimulation, while CD86 plays a protective role mediated through IL-4 or IL-10 production." (PMID 24472094, 2014). "The percentage of pDC that expressed the ligand for PD-1, PD-L1, increased over the duration of sepsis, as did expression of CD86 on mDC." (PMID 22742734, 2012). "Our group and others have previously demonstrated that sepsis is associated with marked an increase in CD80 expression and a loss of constitutively expressed CD86 in mice." (PMID 19672303, 2009). "We first wished to establish that CD28 was serving as the predominant ligand for CD80 or CD86 engagement in sepsis." (PMID 19672303, 2009). "In conclusion, our data describe a differential role for CD80 and CD86 in regulation of inflammation in the innate immune response to sepsis." (PMID 19672303, 2009).